XIST (X inactive specific transcript)
Diseases named in the same sentence as XIST in open-access papers (continued):
Sharing a sentence is not in itself a finding about the gene and the disease.
bladder cancer (continued). "Lnc XIST promotes bladder cancer cell growth and metastasis by regulating miR-139-5p mediated Wnt/β-catenin signaling." (PMID 34367236, 2021). "In bladder cancer cells, XIST serves as a molecular sponge for miR-200c through which it enhances colony formation, self-renewal capacity and EMT in cancer stem cells -like cells." (PMID 34179019, 2021). "In bladder cancer, several lncRNA/miRNA axes have acted as regulators of cancer metastasis, including lncRNA H19/miR-29b, lncRNA XIST/miR-124 and lncRNA UCA1/miR-196a." (PMID 33902589, 2021). "Together with the results of the dual luciferase reporter assay, this demonstrated that XIST directly forms a complementary base pair with miR-200c and acts as a molecular sponge of miR-200c to regulate the biological functions of bladder cancer cells." (PMID 29559853, 2018). "Together with the results of IHC assays, these data suggest the growth-promoting effect of lncRNA XIST both in vitro and in vivo in human bladder cancer." (PMID 29559853, 2018). "In contrast, lncRNA XIST has positive effects on the stemness properties and tumourigenicity of human bladder cancer cells." (PMID 29559853, 2018). "This study aimed to examine the relationship between lncRNA XIST and miR-200c and to assess their functions in the regulation of the stemness properties and tumourigenicity of human bladder cancer stem cell (BCSC)-like cells." (PMID 29559853, 2018). "In bladder cancer, XIST modulates the proliferation, invasion and migration of cancer cells via interacting with miR-124." (PMID 30463570, 2018). "In this study, we found that XIST might influence bladder cancer progression through the miR-15a-5p/MN1 signaling axis." (PMID 40308577, 2025). "In bladder cancer, several studies have highlighted the potential role of XIST." (PMID 40308577, 2025). "We further investigated whether the effects of XIST on bladder cancer cell functions are mediated through FZD2." (PMID 40308577, 2025). "Functional experiments demonstrated that XIST knockdown significantly inhibited bladder cancer cell proliferation, migration, and invasion, effects which could be reversed by FZD2 overexpression." (PMID 40308577, 2025). "Mechanistically, lncRNA XIST could sponge miR-129-5p to regulate TNFSF10 expression in bladder cancer." (PMID 38446257, 2024). "All those results further demonstrated that lncRNA XIST could sponge miR-129-5p to regulate TNFSF10 expression in bladder cancer through these binding sites." (PMID 38446257, 2024). "Based on this, lncRNA XIST could sponge miR-129-5p to modulate TNFSF10 expression in bladder cancer through the predicted binding site in terms of the mechanism." (PMID 38446257, 2024). "XIST, an elevated lncRNA in bladder cancer, inhibition of which could suppress the progression of BC." (PMID 38446257, 2024). "Furthermore, compared with adjacent tissues, lncRNA XIST and miR-129-5p were lowly expressed (P < 0.01) in bladder cancer tissues, and TNFSF10 was highly expressed (P < 0.001)." (PMID 38446257, 2024). "Hence, the study revealed a novel regulatory mechanism of lncRNA XIST to promote bladder cancer progression through modulating miR-129-5p /TNFSF10 axis." (PMID 38446257, 2024). "Moreover, XIST can promote proliferation and metastatic ability of bladder cancer cells via modulating miR-139-5p expression and subsequent regulation of Wnt/β-catenin signaling pathway." (PMID 34179019, 2021). "In bladder cancer, XIST has been found to be up-regulated parallel with up-regulation of AR." (PMID 34831421, 2021). "XIST can also regulate the biological processes of bladder cancer cells by acting on miR-124." (PMID 33364236, 2020).
bladder cancer (continued). "The effect of miR-200c and lncRNA XIST in bladder cancer and a potential relationship between miR-200c and XIST remain largely unknown." (PMID 29559853, 2018). "Therefore, this study aimed to explore the function and regulatory mechanism of XIST and miR-200c in the maintenance of the stemness properties and tumourigenicity of human bladder cancer cells." (PMID 29559853, 2018). "LncRNA XIST may act as an inhibitor of miR-200c to regulate the stemness properties and tumourigenicity of bladder cancer cells, and our findings might reveal a potential strategy of targeting XIST for bladder cancer therapy." (PMID 29559853, 2018). "The mechanism and function of XIST and miR-200c in the pathogenesis of bladder cancer remain largely unknown." (PMID 29559853, 2018). "These evidences may suggest a relationship between miR-200c and XIST influencing the biological functions of bladder cancer cells." (PMID 29559853, 2018). "Furthermore, we examined whether the impact of XIST on bladder cancer cell functions is mediated by MN1." (PMID 40308577, 2025). "Furthermore, SPRY4-IT1, MALAT1, linc-UBC1, lncRNA-LET, ZEB2-AS1, XIST, PVT1, and SNHG16 were significantly associated with lymph node metastasis status in patients with bladder cancer." (PMID 29899709, 2018). "LncRNAs, such as MALAT1, HOTAIR, TUG1, XIST and so on, could promote cancer cell proliferation, invasion and/or migration, including multiple myeloma, triple-negative breast cancer, cervical cancer, pancreatic cancer, bladder cancer, as well as thyroid cancer." (PMID 30463570, 2018). "We evaluated the expression of the XIST/miR-15a-5p/MN1 axis in tissue samples from 50 male and 50 female bladder cancer patients." (PMID 40308577, 2025). "Our findings indicate that XIST and MN1 promote the proliferation and migration of bladder cancer cells, while miR-15a-5p exerts inhibitory effects on these processes." (PMID 40308577, 2025). "LncRNA XIST and TNFSF10 were highly expressed and miR-129-5p was low expressed (P < 0.05) in bladder cancer cell line." (PMID 38446257, 2024). "Of these, XIST, H19, MALAT1, MEG3 play a role in tumor proliferation, suppression, and metastasis of bladder cancer." (PMID 31379598, 2019). "For the XIST, high expression of XIST was related to larger tumor size and higher TNM stage after we pooled OR, suggesting that XIST can serve as a valuable biomarker for predicting tumor size and TNM stage in patients with bladder cancer." (PMID 29899709, 2018). "Compared to adjacent non-cancerous tissues, XIST expression was significantly upregulated in both female and male bladder cancer tissues, with a more pronounced increase in females." (PMID 40308577, 2025). "In the bladder cancer cells TCC-SUP, EJ, SW780, and UM-UC-3, XIST and AR are up-regulated." (PMID 33919565, 2021). "Our present study suggests that lncRNA XIST knockdown inhibits the stemness properties and tumourigenicity by sponing miR-200c in BCSC-like cells and reveals a potential strategy of targeting XIST for bladder cancer therapy." (PMID 29559853, 2018).
glioblastoma (24 papers, 2016 to 2024). The most malignant astrocytic tumor (WHO grade IV). "Despite its original roles in X-chromosome dosage compensation, XIST also plays a significant role in regulating cell growth, development, and is implicated in various cancers, including glioblastoma." (PMID 39015773, 2024). "It has been demonstrated that XIST knockdown exhibited tumor-suppressive impacts on glioblastoma CSCs by lowering cell proliferation, migration, and invasion as well as triggering apoptosis via up-regulation of miR-152." (PMID 39170516, 2024). "Instead, among their few marker genes was ATF5, which plays a neuroprotective role during endoplasmic reticulum stress, and XIST, which is upregulated across a wide range of cancers, including glioblastoma." (PMID 38848215, 2024). "In glioblastoma cells, knocking down the expression of XIST also significantly reduced the glucose uptake of glioblastoma cells and helped to inhibit tumor growth." (PMID 36035993, 2022). "It has been previously demonstrated that lncRNA XIST can control the growth and glucose metabolism in glioblastoma cells via the insulin receptor substrate 1 (IRS1)/the phosphoinositide 3-kinase (PI3K)/protein kinase B(Akt) pathway." (PMID 36035993, 2022). "XIST also acts as a molecular sponge for miR-429 in glioblastoma cells, and the negative regulation of XIST contributes to the repression of glioblastoma cell metastatic and angiogenic potential." (PMID 34316694, 2021). "XIST silencing has suppressed viability, migration, invasiveness, hypo-responsiveness to apoptotic stimuli, and glucose metabolism in glioblastoma." (PMID 34179019, 2021). "Another study in glioblastoma has shown the role of Steroid receptor coactivator-1 (SRC-1) in the regulation of XIST at posttranscriptional level." (PMID 34179019, 2021). "The sex chromosome dosage compensation lncRNA XIST is upregulated in glioblastoma cells, and its depletion inhibited glioblastoma angiogenesis via ZO2 (tight junction protein ZO-2) and FOXC1 (forkhead box C1) transcriptional inactivation." (PMID 34316694, 2021). "Attenuation of cell growth and glucose metabolism was seen in glioblastoma cells following knockdown of XIST." (PMID 33980320, 2021). "In fact, the impact of SRC-1 in enhancement of stemness features in glioblastoma is mediated through XIST." (PMID 34179019, 2021). "Yao elucidated that knockout of XIST exerted tumor suppressive functions by inhibiting glioblastoma stem cell proliferation, migration and invasion as well as promoting apoptosis." (PMID 32489472, 2020). "XIST RNA is upregulated in glioblastoma cells and its depletion inhibits glioblastoma angiogenesis by Zonula Occludens 2 (ZO-2) and Forkhead Box C1 (FOXC1) transcriptional inactivation." (PMID 32283739, 2020). "Studies have proved that XIST impaired formation of neurospheres of glioblastoma via interaction with miR-152 and KLF2." (PMID 29100288, 2017). "For example, knockdown lncRNA XIST exerts tumor suppressive functions by up-regulating miR-152 in human glioblastoma stem cells." (PMID 28881797, 2017). "A recent study demonstrated that knockdown of lncRNA XIST exerted tumor-suppressive effects in human glioblastoma stem cells through up-regulating miR-152." (PMID 27620004, 2016). "For example, lncRNA XIST promotes human glioblastoma stem cells proliferation, migration and invasion by sponging miR-152." (PMID 26840083, 2016). "In addition, XIST, post-transcriptionally regulated by Steroid Receptor Coactivator 1, influences the stemness of glioblastoma cells by modulating the expression of Kruppel-like factor 4 through the XIST/miR-152 axis." (PMID 39015773, 2024). "Additionally, SRC-1 was shown to elevate glioblastoma stemness by modulating the XIST/miR-152/KLF4 axis, which provided a new diagnostic and therapeutic biomarker for glioblastomas." (PMID 34930117, 2021). "XIST expression is also upregulated in glioma and glioblastoma stem cells." (PMID 32751207, 2020).
glioblastoma (continued). "Upregulation of XIST in MM and glioblastoma may represent a counter regulatory mechanism balancing enhanced miR-21 expression." (PMID 32751207, 2020). "Overexpression of XIST has been observed in non-small cell lung cancer and glioblastoma." (PMID 29100288, 2017). "Finally, in glioblastoma, the lncRNA XIST was revealed to regulate glucose metabolism by targeting GLUT1 and GLUT3 through the miR-126-dependent insulin receptor substrate 1 (IRS1)/PI3K/Akt pathway and to positively control glioblastoma cell growth in vivo and in vitro." (PMID 32765426, 2020). "It was also discovered that miR-152 and XIST are located in the same RISC complex, pointing to a potential direct interaction in glioblastoma CSCs." (PMID 39170516, 2024). "Therefore, targeting XIST may represent a promising therapeutic approach in glioblastoma." (PMID 39015773, 2024). "The following lncRNAs engaged in glioblastoma therapy resistance were selected: MALAT1, CASC2, H19, TUSC7, XIST, RP11-838N2.4, DLX6-AS1, GLIDR, MIR210HG, SOX2-OT." (PMID 33245508, 2022). "XIST RNA also acts as a molecular sponge for miR-429 in glioblastoma cells and the negative modulation of XIST contributes to repression of glioblastoma cells metastatic and angiogenic potential." (PMID 32283739, 2020). "Up-regulation of a number of oncogenic lncRNAs such as H19, MALAT1, SNHGs, MIAT, UCA, HIF1A-AS2 and XIST in addition to down-regulation of other tumor suppressor lncRNAs namely GAS5, RNCR3 and NBAT1 indicate the role of these lncRNAs in the pathogenesis of glioblastoma." (PMID 33634032, 2020).
pancreatic cancer (23 papers, 2017 to 2025). "In cancers, such as colon cancer, pancreatic cancer, and cervical cancer, the levels of the XIST can be elevated and are associated with cell proliferation, apoptosis, and metastasis." (PMID 36038831, 2022). "Similarly, in pancreatic cancer, highly-expressed XIST is linked to the unfavorable prognosis of the patients and can facilitate the proliferation of cancer cells by impeding miR-133a expression." (PMID 33942699, 2021). "LncRNA XIST regulates the EGF receptor to promote TGF-β1-induced EMT in pancreatic cancer by acting as a sponge for miR-34a, which has been reported to regulate various cell processes, including EMT, in many malignant tumors." (PMID 35819532, 2022). "Knockdown of lncRNA XIST counteracts the effect of ZEB1 by promoting metastasis through the upregulation of miR-429, which identified the critical axis of XIST/miR-429/ZEB1 in pancreatic cancer migration, invasion and EMT." (PMID 35819532, 2022). "As a result, a number of investigators focused on the role of XIST in the regulation of pancreatic cancer." (PMID 34930117, 2021). "It was further demonstrated that XIST promoted pancreatic cancer cell progression through upregulating EGFR, iASSP, YAP, ZEB1, TGF-β2, and Notch1 by modulating miR-133a, miR-140/miR-124, miR-34a, miR-429, miR-141-3p, and miR-137, respectively." (PMID 34930117, 2021). "In pancreatic cancer, XIST contributes to improve cell migration, invasion, and EMT capacities by acting as a miR-429 molecular sponge to regulate ZEB1 expression." (PMID 32127028, 2020). "In this study, XIST was specifically upregulated in pancreatic carcinoma tissues and cell lines; a higher XIST expression was correlated to poorer clinicopathologic features." (PMID 29371940, 2017). "Similarly, XIST regulates ZEB1 expression in pancreatic cancer by sponging miRNA-429 to promote migration, invasion, and EMT." (PMID 36038831, 2022). "miR-141-3p is another miRNA which has been shown to be sponged by XIST in pancreatic cancer cells." (PMID 34179019, 2021). "A mechanistic analysis showed that miR-34a-5p was a target of XIST and could rescue the malignant activities mediated by XIST in pancreatic cancer." (PMID 34930117, 2021). "Long non-coding RNA XIST exerts oncogenic functions in pancreatic cancer via miR-34a-5p." (PMID 31747939, 2019). "XIST showed to be an independent prognostic factor for pancreatic cancer." (PMID 29371940, 2017). "Additionally, lncRNA XIST regulates miR-185 in both gastric and pancreatic cancers." (PMID 36287119, 2022). "LncRNA XIST could induce proliferation in pancreatic cancer cells." (PMID 33081752, 2020). "Taken together, our data indicated that XIST might be an oncogenic lncRNA that promoted proliferation of PC cell line through inhibiting miR-140/miR-124 expression and promoting cell cycle-related factor expression, and could be regarded as a therapeutic target in human pancreatic carcinoma." (PMID 29371940, 2017). "In pancreatic cancer, miR-133a could exert the anticarcinogenic activity by directly targeting FSCN1, conversely, inhibition of miR-133a by LncRNA XIST could upregulate EGFR expression to accelerate PNI of pancreatic cancer." (PMID 34187567, 2021).
thyroid cancer (20 papers, 2018 to 2024). "To date, lncRNA XIST has been targeted in thyroid cancer using, e.g., siRNA, short hairpin RNA (shRNA), and TGF-β." (PMID 39458944, 2024). "Artemisinin, an antimalarial drug, suppresses the pro-oncogenic effect of XIST and inhibits aerobic glycolysis, proliferation, and metastatic potential of thyroid cancer cells through the degradation of hypoxia-inducible factor 1α (HIF-1α)." (PMID 39458944, 2024). "In thyroid carcinoma, XIST acts as a ceRNA sponging miR-34a and competes with MET for miR-34a binding." (PMID 39030557, 2024). "The ceRNA activity of XIST versus miR-34a has an oncogenic effect in two different tumors, thyroid cancer and nasopharyngeal carcinoma, due to de-repression of different targets in different cell contexts, i.e., MET and E2F3, respectively." (PMID 35054794, 2022). "They further demonstrated that lncRNA XIST was significantly up-regulated and miR-34a was under expressed in Thyroid cancer." (PMID 35453680, 2022). "A previous report demonstrated that reduced expression of XIST led to inhibition of tumor growth in thyroid cancer." (PMID 34295808, 2021). "The molecular mechanism indicated that XIST functions as an oncogene with respect to growth, invasion, and migration by modulating miR-141 in thyroid cancer." (PMID 34930117, 2021). "Overall, these data indicated that XIST has an oncogenic role in thyroid cancer and represents a new therapeutic target." (PMID 34930117, 2021). "A study showed elevated levels of XIST and reduced levels of miR-34a in thyroid cancer tissues and cell lines." (PMID 32219093, 2020). "More importantly, higher XIST expression was correlated with poorer prognosis in patients with thyroid cancer, indicating the potential role of XIST in thyroid cancer pathopoiesis." (PMID 30463570, 2018). "Consistent with that in tissue samples, XIST expression was significantly increased in thyroid cancer cell lines, more up-regulated in KAT18 and FTC113 cells, compared to TEC." (PMID 30463570, 2018). "Here, we demonstrate that XIST negatively interacts with miR-34a to modulate the cell proliferation and tumor growth of thyroid cancer through miR-34a downstream MET-PI3K/AKT signaling." (PMID 30463570, 2018). "To further understand the molecular mechanism of XIST in thyroid cancer, we searched GEO database for dysregulated miRNAs in thyroid cancer tissues." (PMID 30463570, 2018). "XIST was significantly up-regulated in thyroid cancer tissues and cell lines; XIST knockdown suppressed the cell proliferation in vivo and the tumor growth in vitro." (PMID 30463570, 2018). "In the present study, we revealed that XIST knockdown dramatically suppressed the cell proliferation of thyroid cancer cells in vivo, and the tumor growth in vitro, which is consistent with previous studies in other cancers." (PMID 30463570, 2018). "The survival time of the patients with thyroid cancer possessing a lower XIST expression was longer." (PMID 30463570, 2018). "MET is a receptor tyrosine kinase that promotes cell proliferation through PI3K/AKT signaling and miR-34a is considered to be a tumor suppressor targeting MET, thus XIST promotes the proliferation of thyroid cancer by down-regulating miR-34a and increasing MET." (PMID 39030557, 2024). "Moreover, lncRNA XIST knockdown inhibits cell proliferation in-vivo and in-vitro in thyroid cancer cell lines." (PMID 35453680, 2022). "Similarly, miR-34a is also under-expressed in NSCLC and recently it was observed that miR-34a is is directly inhibited by lncRNA XIST in thyroid cancer." (PMID 35453680, 2022). "XIST also binds to miR-34a and elicits proliferation and tumor development in thyroid cancer." (PMID 32591022, 2020). "Similarly, the up-regulation of X-inactive specific transcript (XIST) in thyroid cancer was demonstrated to activate the PI3K/Akt pathway via sponging miR-34a and the subsequent rescue of MET, a well-known oncogene in thyroid cancer." (PMID 33158279, 2020).